NMUR1 (neuromedin U receptor 1)
Description:
G protein-coupled receptor for the neuropeptides neuromedin-U (NMU) and neuromedin-S (NMS). Functionally, is involved in pleiotropic roles, including regulation of feeding, energy balance, blood pressure and smooth muscle contraction (By similarity). Additionally modulates hormone release and inflammatory responses in a tissue- and receptor-dependent manner (By similarity). Mechanistically, upon ligand binding, couples to Galpha proteins, namely GNAQ/Gaq or GNA11/Ga11 and GNAI1/Gai subunits. GNAQ/Gaq or GNA11/Ga11 coupling activatse a phospholipase C (PLC), hydrolyzing PIP2 (phosphatidylinositol 4,5-bisphosphate) into DAG (diacylglycerol) and IP3 (inositol trisphosphate) and mobilizing intracellular calcium via IP3 receptors on the endoplasmic reticulum. Also couples to GNAI1/Gai to inhibit forskolin-stimulated cAMP accumulation. In pancreatic beta cells, through neuromedin U-25, regulates insulin secretion where it coupled to GNAI2 and GNAO1, resulting in reduced intracellular Ca2+ influx and cAMP levels (By similarity). Through neuromedin U-25 in Th2-type T cells, enhances type 2 cytokine secretion and modulates inflammatory responses via activation of PLC-calcineurin-MEK and PI3K signaling pathways (By similarity).
Synonyms: FM-3; GPR66; GPC-R; NMU1R; (FM-3); FM3
Tractability: Small molecule: it belongs to a druggable protein family. Antibody: its Gene Ontology location is reachable by antibodies, with high confidence; UniProt places it where antibodies can reach, with medium confidence; UniProt predicts a signal peptide or a membrane-spanning region. PROTAC: a small molecule that binds it is known.
Target class: Peptide receptor (family A GPCR); Membrane receptor; Neuromedin U receptor; Family A G protein-coupled receptor; Short peptide receptor (family A GPCR)
Gene: Protein-coding gene on chromosome 2 (231,523,187 to 231,530,445, reverse strand). Ensembl gene ENSG00000171596.
Subcellular location: Cell membrane
Pathways (Reactome):
Signal Transduction: G alpha (i) signalling events; G alpha (q) signalling events; Peptide ligand-binding receptors
Gene Ontology:
Molecular function: G protein-coupled receptor activity; neuromedin U binding; neuromedin U receptor activity; neuropeptide receptor activity
Biological process: adenylate cyclase-inhibiting G protein-coupled receptor signaling pathway; calcium-mediated signaling; neuropeptide signaling pathway; phospholipase C-activating G protein-coupled receptor signaling pathway; positive regulation of calcium-mediated signaling; G protein-coupled receptor signaling pathway; chloride transport
Cellular component: membrane; plasma membrane
Genetic constraint (gnomAD): Loss-of-function variants: 19 observed, 19.92 expected, observed/expected ratio (o/e) 0.95, 90% interval 0.66 to 1.4. The upper end of that interval is the gene's LOEUF score, 1.4, which puts it in group 5 of 6, group 1 being the genes least tolerant of losing a copy. Missense variants: 529 observed, 604.72 expected, observed/expected ratio (o/e) 0.87, 90% interval 0.81 to 0.94. Synonymous variants: 258 observed, 269.52 expected, observed/expected ratio (o/e) 0.96, 90% interval 0.86 to 1.06.
Homologues: Orthologues: chimpanzee NMUR1 (99% identical), macaque NMUR1 (92% identical), pig NMUR1 (80% identical), dog NMUR1 (79% identical), rabbit NMUR1 (76% identical), mouse Nmur1 (73% identical), rat Nmur1 (69% identical), tropical clawed frog nmur1 (51% identical), zebrafish nmur1a (50% identical), zebrafish nmur1b (48% identical), zebrafish nmur3 (42% identical), Drosophila melanogaster CapaR (31% identical), and 5 more. Paralogues in human: NMUR2 (42% identical), MLNR (27% identical), GHSR (26% identical), NTSR1 (25% identical), NTSR2 (25% identical), TRHR (25% identical), GPR39 (24% identical), EDNRA (20% identical), EDNRB (19% identical), GRPR (19% identical), NMBR (19% identical), GPR37L1 (19% identical), and 3 more.
Diseases named in the same sentence as NMUR1 in open-access papers:
NMUR1 is named in the same sentence as 32 diseases in open-access papers, as found by Europe PMC text mining. Sharing a sentence is not in itself a finding about the gene and the disease. The quoted sentences say what the papers report.
breast carcinoma (4 papers, 2017 to 2025). "Of the key genes unique to the luminal A breast cancer subtype, the expression levels of only NMUR1 and NCAM1 were associated with patient survival time (P < 0.05)." (PMID 33066779, 2020). "Bioinformatic approaches revealed NMUR1 as a novel key pathogenic gene in luminal A breast cancer, which may be a potential target for clinical therapy." (PMID 41262242, 2025). "NMUR1 and NCAM1 are novel key disease-causing genes for luminal A breast cancer, and STIL is a novel key disease-causing gene for basal-like breast cancer." (PMID 33066779, 2020). "We found that luminal A breast cancer patients with high expression of NMUR1 and NCAM1 had statistically worse overall survival than patients with below-median levels of expression." (PMID 33066779, 2020). "Based on the TCGA data set overall comprising 1,082 breast cancer samples, we demonstrated abundant NMUR1 expression in basal-type and normal-like breast cancers." (PMID 28423716, 2017). "In summary, we identified NMUR1 and NCAM1 as novel key genes associated with the development, progression, and prognosis of luminal A breast cancer, and STIL as a new target with the prognosis of basal-like breast cancer." (PMID 33066779, 2020). "We identified NMUR1 and NCAM1 as novel key genes associated with the development, progression, and prognosis of luminal A breast cancer, and STIL as a novel key gene associated with the prognosis of basal-like breast cancer." (PMID 33066779, 2020). "Thus, we predict that inhibition of NMUR1 and NCAM1 could represent a novel strategy to improve the treatment of luminal A breast cancer." (PMID 33066779, 2020). "The roles of NMUR1 and NCAM1 in breast cancer have not been reported." (PMID 33066779, 2020).
asthma (3 papers, 2021 to 2025). "To investigate the expression of NmUR1 in asthma, we compared the levels of NmUR1 in type 2 lymphocytes between healthy individuals and patients with asthma." (PMID 35810259, 2022). "In this study, we investigated the expression of NmU in human blood and airways, the expression of NmUR1 in human immune cells, especially type 2 cells, and compared the expression in peripheral blood and lung tissue between healthy controls and patients with asthma." (PMID 35810259, 2022). "Therefore, our results revealed a previously unknown regulation of NmUR1 expression by cell activation, which could happen during allergic immune response in asthma." (PMID 35810259, 2022). "However, it has been shown that NMUR1 expression is suppressed under high-dose ICS treatment, suggesting that the NMU–NMUR1 pathway may be insufficiently functional in severe asthma or GC-resistant conditions." (PMID 40305320, 2025).
colorectal cancer (3 papers, 2021 to 2026). A primary or metastatic malignant neoplasm that affects the colon or rectum. "Although NMUR1 was detected in both normal and tumour samples, its expression was significantly decreased in colorectal carcinoma at all stages, which was then confirmed in paired samples (n = 50)." (PMID 34493299, 2021).
ovarian carcinoma (3 papers, 2015 to 2024). A malignant neoplasm originating from the surface ovarian epithelium. "The expression of NMUR1 (NMU receptor 1) in HEK-293T cells has been used to demonstrate that NMU signaling suppresses proliferation of SKOV-3 ovarian cancer cells." (PMID 38921161, 2024). "Validation of NMU, NMUR1, and NMUR2 levels in samples of patients with ovarian cancer and in paired normal adjacent tissues (n = 100) showed that in this type of tumour, the level of NMU expression was elevated (941 fold)." (PMID 31492042, 2019). "Overexpression of NMUR2S significantly suppresses NMU downstream signaling and the proliferation rate of SKOV-3 ovarian cancer cell line, which expresses NMUR2 dominantly and NMUR1 moderately." (PMID 26317338, 2015). "Specifically, only monocytic leukemia-derived THP-1, ovarian carcinoma-derived NIH:OVCAR-3 and ovarian carcinoma-derived SKOV-3 exhibited a higher NMUR1 expression level." (PMID 26317338, 2015). "Taken together, these findings suggest that up-regulation of NMU signaling may help promoting ovarian cancer progression and that this effect can be reversed by introduction of NMUR2S, which can potentially heterodimerize with NMUR2 and NMUR1 to dampen NMU signaling." (PMID 26317338, 2015).
renal carcinoma (3 papers, 2011 to 2025). A carcinoma arising from the epithelium of the renal parenchyma or the renal pelvis. "NMUR1 is a neuropeptide associated with energy homeostasis and tumor progression, and renal cancer cells can express functional NMUR1 and stimulate tumor migration." (PMID 41262242, 2025). "We also show that renal cancer cells express a functional NMU receptor (NMUR1), and that NMU stimulates migration of renal cancer cells." (PMID 21791076, 2011). "To determine whether renal cancer cells might respond to NMU we first examined expression of the receptors NMUR1 and NMUR2." (PMID 21791076, 2011).
lung carcinoma (2 papers, 2022 to 2024). "The results obtained reveal that NMUR1 had a significantly lower expression level in COAD, LUAD, and so forth, which is consistent with recent publications in CRC and lung cancer." (PMID 39055918, 2024).
Obesity (2 papers, 2021 to 2022). Accumulation of substantial excess body fat. "A further investigation to analyze NMU/NMUR1 pathway in MC may provide a link between obesity and KOA pathology." (PMID 36232539, 2022). "Further investigation to analyze the NMU/NMUR1 pathway in MC may provide a link between obesity and KOA pathology." (PMID 36232539, 2022). "This evidence suggests that a stable NMUR1 agonist for peripheral administration could be a potential candidate for treating obesity and diabetes." (PMID 33921859, 2021). "Together with NMUR1, which is expressed in ILC2s, NMU is a crucial modulator of both obesity and asthma pathogenesis; further studies could provide some new mechanisms mediated by the NMU system in the pathogenesis of these disorders." (PMID 33921859, 2021). "Therefore, our findings suggest that elevated NMUR1 and CPA3 expression is associated with obesity but not age." (PMID 36232539, 2022).
pancreatic ductal adenocarcinoma (2 papers, 2024 to 2025). An infiltrating adenocarcinoma that arises from the epithelial cells of the pancreas. "Inhibition of NMUR1 upregulated the antitumor activity of CD8+ T cells and the glycolytic process of tumor cells in the tumor microenvironment of pancreatic ductal adenocarcinoma." (PMID 41262242, 2025).
parasite infection (2 papers, 2022 to 2024). "Recent studies have shown that NMUR1 is expressed on ILC2s membrane in the lamina propria of the small intestine, and the expression of NMU can be significantly increased when M. benedeni infected, and ILC2s can be effectively activated by NMUR1 and act as the anti-parasitic infection functions." (PMID 38956647, 2024).
Sepsis (2 papers, 2021 to 2022). Sepsis is defined as life-threatening organ dysfunction caused by a dysregulated host response to infection. "Neuromedin U activated lung ILC2s by NMUR1, which further promoted IL-17A secretion and IL-17A-dependent γδ T cell amplification, which in turn exacerbated sepsis." (PMID 35273971, 2022). "To determine the role of NMU-NMUR1 signaling in sepsis-induced inflammation, we measured the expression of NMU in the lungs and NMUR1 expression in ILC2s following CLP." (PMID 33995408, 2021). "In this study, we demonstrate that sepsis-induced NMU acting through NMUR1 on lung ILC2s initiates the ILC2 activation, which, in turn, promotes IL-17A-producing γδ T cell expansion and secretion of IL-17A." (PMID 33995408, 2021). "In this study, we discovered that the lung expression of NMU is elevated during sepsis, and NMU receptor NMUR1 is selectively expressed in the lung ILC2s." (PMID 33995408, 2021). "In sepsis, NMU acting through NMUR1 in lung ILC2s initiates the ILC2 activation, which, in turn, promote IL-17A-producing γδ T cell expansion and secretion of IL-17A." (PMID 33995408, 2021). "In this study, using a mouse sepsis model induced by CLP, we show that NMU acting through NMUR1 on lung ILC2s initiates the ILC2 activation, which, in turn, promotes IL-17A-producing γδ T cell expansion and IL-17A secretion." (PMID 33995408, 2021).
Arthritis (1 paper, 2012). Inflammation of a joint. "Similarly, we have shown here that autoantibody-induced arthritis was unimpaired in these same Nmur1/Nmur2-deficient mice." (PMID 22314006, 2012). "Mice lacking NMUR1, NMUR2 or both receptors developed arthritis in an essentially indistinguishable way from control mice." (PMID 22314006, 2012).
breast tumors (1 paper, 2017). "Interestingly, NMU tends to predict poor survival in breast tumors presenting low levels of NMUR1 mRNA." (PMID 28423716, 2017).
endometrial cancer (1 paper, 2016). Primary or metastatic malignant neoplasm involving the endometrium (mucous membrane that lines the endometrial cavity). "Furthermore, the level of NMUR2 was much higher than that of NMUR1 in all three endometrial cancer lines, suggesting that NMUR2 is also the main receptor type involved in conducting NMU signaling in these cells." (PMID 26849234, 2016). "Using clinical samples from patients with endometrial cancer, we also confirmed the transcript level of NMUR2 is higher than that of NMUR1 especially in the high grade tumors, consistent with the receptor profiles shown in the normal mouse uterus." (PMID 26849234, 2016).
endothelial dysfunction (1 paper, 2024). In vascular diseases, endothelial dysfunction is a systemic pathological state of the endothelium (the inner lining of blood vessels) and can be broadly defined as an imbalance between vasodilating and vasoconstricting substances produced by (or acting on) the endothelium. "Therefore, we speculated that the endothelial dysfunction characteristic of PE patients with high NMUR1 expression may result from NMU secreted by endothelial cells, activating NMUR1-positive endothelial cells and infiltrating macrophages." (PMID 38846957, 2024).
head and neck squamous cell carcinoma (1 paper, 2021). A squamous cell carcinoma that arises from any of the following anatomic sites: lip and oral cavity, nasal cavity, paranasal sinuses, pharynx, larynx, and salivary glands. "Neuromedin U receptor 1 (NMUR1) is one of the receptors of Neuromedin U. A previous study reported that the methylation of the NMUR1 gene was related to poor survival in patients with head and neck squamous cell carcinoma." (PMID 35069695, 2021).
helminth infection (1 paper, 2021). "In a mice model of worm infection in the lungs and intestine, stimulation of ILC2s with NMU led to strong and immediate production of tissue protection and innate inflammatory cytokines in an NMUR1-dependent manner, thereby alleviating worm burden." (PMID 33995408, 2021).
leukoaraiosis (1 paper, 2009). "An interaction between NMUR1 (a G-protein coupled activator that appears to be involved in regulation of food intake) and GPR55 (a G-protein coupled receptor) also points to genetic variation in signal transduction pathways playing a role in leukoaraiosis development." (PMID 19351393, 2009).
oropharyngeal carcinoma (1 paper, 2020). Carcinoma, predominantly squamous cell, arising from the epithelial cells of the oropharynx. "In addition, the site-specific analysis revealed that abnormal CpG island hypermethylation in the GHSR and NMUR1 promoters was independently associated with aggressive clinical behavior in oropharyngeal cancer." (PMID 31974445, 2020). "For correlation analysis of the association between tumor HPV status, GHSR methylation status, and NMUR1 methylation status with survival, we combined data for all patients with oropharyngeal carcinoma." (PMID 31974445, 2020). "In the current study, we presented the relationship between the methylation status of the GHSR and NMUR1 genes and recurrence in HNSCC, specifically in risk classification of oropharyngeal carcinomas cases with HPV status." (PMID 31974445, 2020). "It is worth noting that the GHSR and NMUR1 methylation status is a strong predictor of poorer survival among patients with HPV-positive oropharyngeal cancer." (PMID 31974445, 2020). "Our results indicate that the methylation status of the GHSR and NMUR1 genes is an independent prognostic indicator for patients with oropharyngeal cancers." (PMID 31974445, 2020). "Furthermore, in HPV-related oropharyngeal cancer (n = 37), GHSR and NMUR1 hypermethylation was significantly associated with shorter DFS (log-rank test, P = 0.003 and P = 0.026, respectively)." (PMID 31974445, 2020). "Methylation of the GHSR and NMUR1 promoters correlated positively with recurrence in oropharyngeal cancer patients, both individually (OR, 3.853; 95% CI, 1.510–9.832; P = 0.005 and OR, 2.872; 95% CI, 1.172–7.037; P = 0.036, respectively) and together (OR, 3.272; 95% CI, 1.216–8.801; P = 0.019)." (PMID 31974445, 2020). "In patients with oropharyngeal cancer (n = 75), GHSR and NMUR1 promoter methylation significantly correlates with survival in surgically treated patients." (PMID 31974445, 2020).
osteoarthritis (1 paper, 2022). A noninflammatory degenerative joint disease occurring chiefly in older persons, characterized by degeneration of the articular cartilage, hypertrophy of bone at the margins and changes in the synovial membrane. "Neuromedin U (NMU) and NMU receptors (NMUR1 and NMUR2) are associated with obesity-related disorders and found in mast cells (MCs), which are elevated in osteoarthritis." (PMID 36232539, 2022).
pancreatic cancer (1 paper, 2019). "The NMUR1 expression was found at the same low level in all pancreatic tissues, but the amount of NMUR2 mRNA detected in pancreatic cancer tissues was 149 times higher compared to healthy tissues." (PMID 31492042, 2019).
preeclampsia (1 paper, 2024). Preeclampsia is a hypertensive disorder of pregnancy that is characterized by new-onset hypertension with proteinuria presenting after 20 weeks of gestation, and depending on mild or severe forms may initially present with severe headache, visual disturbances, and hyperreflexia. "In this study, we observed significant differences in the expression levels of FNBP1L, NMUR1, and PP14571 genes in patients with preeclampsia." (PMID 38846957, 2024).
squamous cell carcinoma (1 paper, 2025). A carcinoma arising from squamous epithelial cells. "NMUR1 was discovered to be extensively dispersed throughout the body's organs and was linked to a poor prognosis in individuals suffering from squamous cell carcinoma of the head and neck." (PMID 40161493, 2025).